CD4 (CD4 molecule)
Diseases named in the same sentence as CD4 in open-access papers (continued):
Sharing a sentence is not in itself a finding about the gene and the disease.
cryptococcosis (continued). "By comparison, a mean global prevalence of cryptococcal infection of 6.0% was reported in outpatients with a CD4 cell count <100/μl from 29 countries." (PMID 31929533, 2020). "Recently, screening for Cryptococcal infection among severely immunosuppressed (CD4<100 cells/ mm3) ART naïve patients have been adopted by the World Health Organisation (WHO)." (PMID 32853215, 2020). "It is also possible that patients who developed CM-IRIS had aberrant or dysregulated CD4+ T cell function during the primary cryptococcal infection resulting in persistent cryptococcal antigen, known to be a risk factor for CM-IRIS." (PMID 31126019, 2019). "The WHO recommends CrAg screening in HIV-infected patients with a low CD4 T-cell count (<100 cells/μL) prior to ART initiation to prevent CM development and cryptococcal infections associated with immune reconstitution inflammatory syndrome." (PMID 31771096, 2019). "The most frequent presentation of cryptococcal infection is subacute meningitis, especially in patients with a CD4+ T Lymphocytes count below 100 cells/μL." (PMID 30832607, 2019). "Early studies have reported the main role of CD4+ T cells and Th1 responses in the protection against cryptococcosis in animal models (45, –, 48)." (PMID 30940711, 2019). "Mfinanga (2015) also showed a significant improvement in retention at 12 months with their screening and treatment of cryptococcal infections and community-based adherence support intervention for patients with <200 CD4 cells/μL." (PMID 30550574, 2018). "Colombia has made some attempts at showing the usefulness of early detection of cryptococcosis in patients with a depleted CD4 count." (PMID 29494502, 2018). "Studies using mouse models of cryptococcosis have demonstrated that Th1 and Th17 CD4+ T cells are important in defense (4, 5, 7, –, 9)." (PMID 29317510, 2018). "Given the importance of CD4+ T cells in defense against cryptococcosis, we next examined the differentiation of Cryptococcus-specific CD4+ T cells in mice infected with Fbp1-deficient or -sufficient yeast." (PMID 29317510, 2018). "We report the case of a patient with HIV infection with a CD4 T lymphocyte cell (CD4) count of 2 cells/mm3, who presented concurrent infection of three opportunistic pathogens: Cryptococcosis, disseminated histoplasmosis and cryptosporidiosis." (PMID 30591013, 2018). "Deaths from cryptococcosis were more common in standard prophylaxis (P = .03) and participants with lower baseline CD4 count (P = .02) or self-reported vomiting (P = .005)." (PMID 29514234, 2018). "Both clinical and experimental studies have shown that Th1-type CD4+ T CMI is critical for protection against cryptococcosis." (PMID 29163469, 2017). "The CD4+ T-cell count was sharply decreased (median, 82/μL; range 7–292/μL) in 53 patients with idiopathic CD4+ T lymphocytopenia and cryptococcosis." (PMID 28035481, 2017). "By the recruitment of granulocytes and macrophages in the lungs and the production of IL-12, TNF-α, and IFN-γ, CD4+ T cells have been shown to protect mice against cryptococcal infection." (PMID 28035481, 2017). "In this study, we analyzed the clinical features, chest images, and prognosis of pulmonary cryptococcosis in patients with different peripheral blood CD4+ T lymphocyte counts." (PMID 29237413, 2017). "According to the current study, we should routinely check CD4 + T cell counts and perform a chest CT scan when the patient is highly suspected to have cryptococcosis." (PMID 29237413, 2017). "In this way, the CD4 + T count can indicate the severity of cryptococcosis and facilitate the estimation of prognosis." (PMID 29237413, 2017). "The neurologist considered the immune suppression effect of azathioprine, the stable status of MG and the low CD4 cell count and decided stopping azathioprine and lowered the methyl prednisolone dose to 4 mg/day for better control of Cryptococcal infection." (PMID 28446137, 2017).
cryptococcosis (continued). "Currently, the related data of CD4 + T cells concerning cryptococcosis were from small sample studies or case reports." (PMID 29237413, 2017). "For patients with CD4+ T-lymphocyte counts lower than 400/μL, the odds ratio of disseminated cryptococcosis was 23.3 (P = 0.005)." (PMID 28035481, 2017). "Articles related to the assessment of the severity of cryptococcosis and prognosis through CD4 + T cells are rare." (PMID 29237413, 2017). "Systematic laboratory-based CRAG screening among those with low CD4 count, followed by lumbar puncture to detect meningitis, allowed reliable ascertainment of disseminated cryptococcosis and cryptococcal meningitis." (PMID 28719610, 2017). "In other words, a count of CD4+ T cells in the peripheral blood of each patient with cryptococcosis should be done routinely." (PMID 28035481, 2017). "Results from multiple studies in both humans and animal models suggest that cell-mediated immunity (CMI) by Th1-type CD4+ T cells is the primary host defense against cryptococcosis." (PMID 29163469, 2017). "According to the description above (infection site/clinical feature/APACHE II scores), the results showed that the CD4+ T-lymphocyte counts can effectively assess the disease severity of cryptococcosis patients." (PMID 29237413, 2017). "In the current study, 17.1% of patients with normal CD4+ T cell counts and cryptococcosis were asymptomatic, and their disease was detected incidentally during routine chest radiography or follow-up for other diseases." (PMID 29237413, 2017). "Collectively, these findings show that early TNF-α signaling is required for the local development of Th1/Th17 CD4+ T cell polarization in the lungs and a protective systemic immune response during cryptococcal infection." (PMID 27406560, 2016). "Morbidity and mortality rates due to cryptococcosis are significantly higher in resource-limited settings and in individuals with impaired CD4+ T cell-mediated immune responses." (PMID 26087178, 2015). "Idiopathic CD4 lymphocytopenia (ICL) was found in 11 patients with cryptococcosis reviewed over a 12-month period with features similar to those of cryptococcal infections in normal hosts." (PMID 26649217, 2015). "Clinical and experimental evidence suggests that protective immunity against cryptococcosis is dependent upon Th1-type CD4+ T cell-mediated immune responses." (PMID 26087178, 2015). "The efficiency of the Δsgl1 strain as a vaccine against cryptococcosis during immune suppression was examined by its administration in CD4+ T-cells depleted mice prior to infection with the WT C. neoformans." (PMID 26322039, 2015). "Surprisingly, the Δsgl1 strain induces a CD4+ T cells independent immunity since previous immunization to infection of immunocompromised mice completely protected these animals against cryptococcosis." (PMID 26500643, 2015). "A reduction in CD4+ T-cells in this population results in aggressive cryptococcosis, which can be life threatening." (PMID 26322039, 2015). "Excluding those transfers would result in a conservative estimate of prevalence of cryptococcal infection in newly diagnosed HIV patients with CD4 < 100 cells/μL in southwest London of 3% (4/153), and 5% (4/84) in Africans." (PMID 23046967, 2013). "The World Health Organization (WHO) recently recommended screening HIV-infected adults with CD4<100 cells/mm3 for serum cryptococcal antigen (CrAg), a marker of early cryptococcal infection, in areas of high CrAg prevalence." (PMID 23626792, 2013). "Since the prevalence of cryptococcal antigenemia is high among ART-naïve persons with low CD4+ T-cell counts, unmasking of cryptococcosis is likely a significant contributor to early mortality." (PMID 24124498, 2013). "Cryptococcal antigen (CrAg), a biologic marker of cryptococcal infection, is detectable in sera a median of 3 weeks (range 5–234 days) before symptoms of meningitis appear, and is most commonly found in patients with CD4<100 cells/mm3." (PMID 23626792, 2013).
cryptococcosis (continued). "Lymphocytes, particularly CD4+ T cells, are important in the cell-mediated immune response to cryptococcosis." (PMID 22007224, 2012). "We evaluated a cohort of 149 consecutive HIV-infected adult inpatients presenting with headache or altered mental status for clinical features, CD4 count, cryptococcal infection, and outcome." (PMID 17493266, 2007). "However, CME is an AIDS-defining disease, and low CD4+ T-cell count is a major susceptibility factor for CME, indicating that the adaptive immune response also plays an important role in controlling cryptococcal infections." (PMID 40444466, 2025). "Thus, sequential point-of-care testing enabled the diagnosis of cryptococcosis in HIV+ individuals with blood CD4 T cell counts ≤200 cells/μl." (PMID 40198673, 2025). "A positive serology for T. gondii could confer protection against cryptococcal infection in the CNS in case of an acceptable CD4 count." (PMID 40142374, 2025). "This aligns with existing evidence suggesting that CD4+ T cell counts below 400 cells/μL substantially increase the risk of disseminated cryptococcosis in non-HIV immunocompromised hosts." (PMID 41245252, 2025). "Under the combined stimulation of cytokines such as IL-2, IL-12, IL-15 and IL-18, NK cells are capable of producing IFN-γ and TNF-α, which promote Th1 polarization of CD4+ T cells and M1 polarization of macrophages, enhancing systemic immunity against cryptococcal infection." (PMID 41017910, 2025). "Most persons with cryptococcosis have quantitative or qualitative CD4+ T-cell dysfunction." (PMID 38980038, 2024). "▪Discontinue secondary prophylaxis if the patient completed initial (induction and consolidation) therapy, received at least 1 year of antifungal therapy, and remains asymptomatic of cryptococcal infection, and CD4+ count ≥ 100 cells/μL with suppressed plasma HIV RNA in response to ART." (PMID 39459894, 2024). "Having demonstrated that cda1∆2∆3∆ cells were avirulent in NSG mice that lacked B and T cells, we next systematically examined the contribution of B cells, CD8+ T cells, and CD4+ T cells to protection against cryptococcosis mediated by the live cda1∆2∆3∆ vaccine." (PMID 38980038, 2024). "In another study, a heat-killed Cryptococcus neoformans Δsgl1 mutant accumulating sterylglucosides protected mice in the absence of CD4+ T cells, a condition that is most often associated with cryptococcosis." (PMID 37367569, 2023). "Importantly, once animals have been vaccinated with heat-inactivated or live short-lived ZNF2oe cells, they are protected against cryptococcosis even when their CD4+ T cells are depleted at the time of fungal challenge." (PMID 37338404, 2023). "Although CD4+ T cells play a role against cryptococcal infection, they could also augment the immunopathological reaction and the Th1-biased response with prominent upregulation of pro-inflammatory cytokines." (PMID 37251371, 2023). "Therefore, there is an urgent need to develop new immunotherapeutic strategies for enhancing the function of CD4+ T-cells to combat cryptococcosis." (PMID 35835754, 2022). "Aiming to interfere with the CM incidence, morbidity, and mortality, the WHO strongly recommends the routine application of antigen detection tests for the diagnosis of cryptococcal infection in asymptomatic HIV-positive patients with CD4 levels < 100/μL in regions with prevalence ≥ 3%." (PMID 36547617, 2022). "Clinical and experimental data have established that CD4+T-cell-mediated immunity (CMI) is essential for the control of cryptococcal infection since this disease occurs mainly in those with impaired CMI including HIV-infected individuals, with an incidence of 30% and a mortality of 30 to 60%2." (PMID 35835754, 2022).
cryptococcosis (continued). "The havoc cryptococcosis has wreaked on the African continent calls for an integrated healthcare approach especially for HIV–positive persons with CD4 lymphocytes count ≤100 cells/μl to include CrAg screening into the national healthcare system guideline of all countries in Africa." (PMID 36006867, 2022). "However, several cases of cryptococcal infections have been reported in MS patients treated with fingolimod and low CD4+ T cell count." (PMID 33530945, 2021). "Among patients with cryptococcosis, 33/51 (65%) presented with counts <50 CD4 cells per μl." (PMID 34536307, 2021). "However, despite attempts to restore and maintain immune response with early antiretroviral therapy (ART) among HIV‐infected individuals with higher CD4 T cells, some persons still present with high incidence of HIV‐associated cryptococcosis." (PMID 32472727, 2020). "The revised WHO guidelines on the management of cryptococcosis advocates for the screening of all HIV-infected patients with a CD4+ T-cell count of ≤ 100 cell/mm3, although a cut-off of ≤ 200 cell/mm3 may be considered." (PMID 32628714, 2020). "At the time of the hospital diagnosis of cryptococcosis, there were 59 participants with a CD4 count ranging from 1–234 cells/μl (median 34, IQR 18–75); only three had a CD4 count >200 cells/μl; five of those participants knew their CD4 count six months prior to their diagnosis of cryptococcosis." (PMID 31830060, 2019). "An older study in Cape Town reported a higher CrAg prevalence of 12% (42/336) among pre-ART HIV-infected adults with CD4 ≤100 cells/mm3 5, and the overall incidence of HIV-associated cryptococcosis has been declining throughout South Africa since the year 200627." (PMID 30804356, 2019). "Thus, CD4+ T cell differentiation along distinct lineages has differential implications for the outcome of cryptococcosis, and can be shaped by host- and fungus-derived factors." (PMID 29317510, 2018). "Our study confirmed that as opposed to underlying disease, the CD4+ T-cell count is a more effective predictor of disseminated cryptococcosis." (PMID 28035481, 2017). "In conclusion, the CD4+ T-cell count is an effective indicator of a patient’s immune status and provides a more accurate estimate of disease severity and prognosis in cases of cryptococcal infection." (PMID 28035481, 2017). "Recent studies have reported that screening of serum cryptococcal antigen may be useful in AIDS patients with CD4 cell count less than 100cells/mm3 in regions with highly endemic for cryptococcal infection." (PMID 29214004, 2017). "The CD4+ T-lymphocyte count in peripheral blood is a simple and more accurate biomarker for predicting severity of infection and clinical outcome in patients with cryptococcosis." (PMID 28035481, 2017). "Thus, the effect of early TNF-α depletion on the polarization/activation of CD4+ T cells during cryptococcal infection needs to be accurately assessed." (PMID 27406560, 2016). "The Δsgl1 strain was also able to protect CD4+ T-cell depleted mice against cryptococcosis." (PMID 26322039, 2015). "Indeed, cryptococcosis is usually observed in late stage HIV infection when CD4 T cell numbers are extremely low." (PMID 26252005, 2015). "Similarly, immunization with a C. neoformans strain genetically engineered to produce IFN-γ, designated H99γ, can induce protective immunity against cryptococcosis in mice depleted of CD4+ T cells." (PMID 26087178, 2015). "Epidemiological evidence clearly points to the importance of adequate CD4+ T-cell mediated immunity in the control of cryptococcal infection, and experimental data suggest that the phenotype of the CD4+ T-cell response to Cryptococcus neoformans influences the outcome of CM." (PMID 25853653, 2015).
cryptococcosis (continued). "This prevalence of cryptococcosis among asymptomatic patients found in our setting emphasizes the importance of screening patients with a low CD4 cell count for cryptococcal antigen, as has been advocated by experts in this field, and as was recently recommended by WHO." (PMID 24476751, 2014). "In a resource-limited setting, screening of patients with CD4+ counts of less than 50 cells/mm3 for cryptococcal infection may even be more clinically relevant as CD4 tests become more available." (PMID 22417404, 2012). "The most important host response to cryptococcal infection is most probably cell-mediated immunity as the effector cells against the yeast include CD4+ and CD8+ lymphocytes, natural killer cells, and activated phagocytes that produce granulomatous inflammation." (PMID 19946453, 2009). "With the ability now to fluorescently sort cytotoxic CD4+ T-cells based on extracellular receptor repertoire, revisiting past experiments could provide information on the role of human cytotoxic CD4+ T-cells during cryptococcosis." (PMID 39452664, 2024). "In previous studies, a live, attenuated Cryptococcus neoformans Δsgl1 mutant accumulating sterylglucosides was found to be avirulent and protected mice from a subsequent lethal infection even in absence of CD4+ T cells, a condition most associated with cryptococcosis (e.g., HIV)." (PMID 35615354, 2022). "Despite some limitations, clinic-based CrAg LFA screening for HIV-infected adults with participants with CD4 < 200 cells/mm3 may be an important tool to help accelerate diagnosis and treatment of HIV-associated cryptococcal infections in order to reduce HIV-associated cryptococcal mortality." (PMID 30804356, 2019). "For our African CRAG positive patients with known time between arrival to the UK and new HIV diagnosis, this ranged from 5 to 16 years, suggesting opportunities for earlier HIV diagnosis and ART, which might have prevented dissemination of latent cryptococcal infection occurring at lower CD4 counts." (PMID 23046967, 2013). "From these data, one may hypothesize that in patients with CD4 count ≤50 cells/μl and a higher cryptococcosis incidence, the prophylaxis strategy in addition to being a more effective strategy for cryptococcal infection prevention is probably associated with an acceptable cost-effective ratio." (PMID 21085478, 2010). "Specifically, the median CD4 count was 49 cells/mm3 (IQR: 21.7 to 112.2) for histoplasmosis and 49 cells/mm3 (15.7 to 86) for cryptococcosis." (PMID 39452647, 2024). "Peripheral blood mononuclear cells (PBMCs) in men have lower adaptive immunity-related (CD3+, CD4+, and CD8+) T-cell percentages during cryptococcal infection than in women." (PMID 37251371, 2023). "Similar findings were found for cryptococcosis, where a very recent analysis of cryptococcal antigen (CrAg) data showed 9.2% (IC95% 7.9–10.7%) of patients with <100 CD4/mm3, which is 3.2% higher than the previous global estimation." (PMID 36547618, 2022). "In contrast, studies examining neurosymptomatic cohorts with extremely low CD4+ T-cell counts and CNS coinfections (eg, toxoplasmosis, CMV encephalitis, cryptococcosis, etc.)have reported HCV in CSF and brain tissue." (PMID 36865569, 2022). "Protection was lost only when both CD4+ and CD8+ T cells were depleted, highlighting a previously unexplored role of fungal-derived SGs as an immunoadjuvant for host protection against cryptococcosis." (PMID 34568097, 2021). "In conclusion, this study highlights the high prevalence of cryptococcal infection and CM in HIV-infected patients with CD4 cell counts < 200/μl." (PMID 31929533, 2020). "The cryptococcal infection should be included for differential diagnosis in HIV-infected patients with fever and cytopenias, especially when CD4+ T lymphocytes count is below 100 cells/μL." (PMID 30832607, 2019).